ZNF286A (zinc finger protein 286A)
Description:
May be involved in transcriptional regulation.
Synonyms: KIAA1874; ZNF286
Tractability: PROTAC: ubiquitination databases record sites on it.
Gene: Protein-coding gene on chromosome 17 (15,699,577 to 15,720,787, forward strand). Ensembl gene ENSG00000187607.
Subcellular location: Nucleus
Subcellular location (Human Protein Atlas): Nucleoli
Pathways (Reactome):
Gene expression (Transcription): Generic Transcription Pathway
Gene Ontology:
Molecular function: protein binding; DNA-binding transcription factor activity, RNA polymerase II-specific; RNA polymerase II cis-regulatory region sequence-specific DNA binding
Biological process: regulation of transcription by RNA polymerase II; regulation of DNA-templated transcription
Cellular component: nucleus
Genetic constraint (gnomAD): Loss-of-function variants: 31 observed, 44.05 expected, observed/expected ratio (o/e) 0.7, 90% interval 0.53 to 0.95. The upper end of that interval is the gene's LOEUF score, 0.95, which puts it in group 4 of 6, group 1 being the genes least tolerant of losing a copy. Missense variants: 440 observed, 574.89 expected, observed/expected ratio (o/e) 0.77, 90% interval 0.71 to 0.83. Synonymous variants: 149 observed, 189.18 expected, observed/expected ratio (o/e) 0.79, 90% interval 0.69 to 0.9.
Homologues: Orthologues: chimpanzee ZNF286A (99% identical), macaque ZNF286A (98% identical), dog ZNF286A (90% identical), rabbit ZNF286A (89% identical), pig ZNF286A (88% identical), guinea pig ZNF286A (87% identical), rat Zfp286a (82% identical), mouse Zfp286 (81% identical). Paralogues in human: ZNF30 (43% identical), ZNF568 (43% identical), ZNF33B (42% identical), ZNF717 (42% identical), ZFP28 (42% identical), ZNF182 (42% identical), ZNF41 (42% identical), ZNF33A (42% identical), ZNF606 (42% identical), ZNF630 (42% identical), ZNF658 (42% identical), ZNF726 (42% identical), and 164 more.
Diseases named in the same sentence as ZNF286A in open-access papers:
ZNF286A is named in the same sentence as 2 diseases in open-access papers, as found by Europe PMC text mining. Sharing a sentence is not in itself a finding about the gene and the disease. The quoted sentences say what the papers report.
COVID-19 (1 paper, 2023). A disease caused by infection with severe acute respiratory syndrome coronavirus 2. "Finally, the relevance of ZFP62–artenimol and the ongoing research on NADH’s role in treating severe COVID-19 symptoms implies that the other predicted drug–target interaction, ZNF286A targeted by NADH, may also be relevant for COVID-19." (PMID 36674947, 2023). "For the two newly predicted COVID-19-related genes, ZFP62 and ZNF286A, there do not exist any drugs targeting their gene products." (PMID 36674947, 2023).
cancer (1 paper, 2022). A tumor composed of atypical neoplastic, often pleomorphic cells that invade other tissues. "Although other members of this family, such as ZNF224 and ZNF217, play important roles in cancer development, the role of ZNF286A has not been studied in any disease." (PMID 36134026, 2022).